LSM10 (LSM10, U7 small nuclear RNA associated)
Description:
Appears to function in the U7 snRNP complex that is involved in histone 3'-end processing. Increases U7 snRNA levels but not histone 3'-end pre-mRNA processing activity, when overexpressed. Required for cell cycle progression from G1 to S phases. Binds specifically to U7 snRNA. Binds to the downstream cleavage product (DCP) of histone pre-mRNA in a U7 snRNP dependent manner.
Synonyms: MGC15749; MST074; MSTP074
Tractability: PROTAC: its protein half-life has been measured.
Gene: Protein-coding gene on chromosome 1 (36,391,238 to 36,397,945, reverse strand). Ensembl gene ENSG00000181817.
Subcellular location: Nucleus
Subcellular location (Human Protein Atlas): Nucleoplasm; Nuclear bodies
Pathways (Reactome):
Metabolism of RNA: SLBP Dependent Processing of Replication-Dependent Histone Pre-mRNAs; SLBP independent Processing of Histone Pre-mRNAs
Gene expression (Transcription): RNA Polymerase II Transcription Termination
Gene Ontology:
Molecular function: protein binding; U7 snRNA binding; histone pre-mRNA DCP binding; RNA binding
Biological process: positive regulation of G1/S transition of mitotic cell cycle; 7-methylguanosine cap hypermethylation; mRNA 3'-end processing by stem-loop binding and cleavage; nuclear histone mRNA catabolic process
Cellular component: Cajal body; nuclear body; nucleoplasm; U7 snRNP; cytoplasmic U snRNP body; nucleus
Genetic constraint (gnomAD): Loss-of-function variants: 7 observed, 8.08 expected, observed/expected ratio (o/e) 0.87, 90% interval 0.49 to 1.59. That is too few expected variants to judge how well the gene tolerates losing a copy. Missense variants: 150 observed, 179.56 expected, observed/expected ratio (o/e) 0.84, 90% interval 0.73 to 0.96. Synonymous variants: 63 observed, 71.32 expected, observed/expected ratio (o/e) 0.88, 90% interval 0.72 to 1.09.
Homologues: Orthologues: chimpanzee LSM10 (100% identical), macaque LSM10 (98% identical), guinea pig LSM10 (92% identical), dog LSM10 (91% identical), mouse Lsm10 (89% identical), pig LSM10 (89% identical), tropical clawed frog lsm10 (70% identical), zebrafish lsm10 (68% identical), zebrafish LSM10 (47% identical), Drosophila melanogaster Lsm10 (25% identical), Caenorhabditis elegans K07A1.15 (21% identical).
Diseases named in the same sentence as LSM10 in open-access papers:
LSM10 is named in the same sentence as 10 diseases in open-access papers, as found by Europe PMC text mining. Sharing a sentence is not in itself a finding about the gene and the disease. The quoted sentences say what the papers report.
breast tumors (1 paper, 2021). "Methylation levels of LSM2, LSM4, and LSM10 were upregulated in primary breast tumors, while LSM6 methylation levels were downregulated." (PMID 34638387, 2021). "Of interest, our findings through DNA methylation level analysis by using UALCAN database also support the consistent trend, which show LSM2, LSM4, LSM10 were upregulated in primary breast tumors, while LSM6 methylation levels were downregulated." (PMID 34638387, 2021).
myeloma (1 paper, 2023). "Finally, binding of PRMT5, MEP50, and pICln to Lsm10/11 heterodimers was observed in a mouse myeloma nuclear extract (lane 7), indicating that the interaction can occur in both the cytoplasmic and nuclear fractions from different mammalian cell lines." (PMID 37562960, 2023). "Readily detectable binding of the methylosome to the Lsm10/11ΔL dimer was also observed in a cytoplasmic extract from mouse myeloma cells (lane 4) and was not abolished by additionally deleting the entire amino-terminal region of Lsm11 (lane 5)." (PMID 37562960, 2023).
tumor (2 papers, 2021 to 2022). "Recent studies suggest that LSM10 may be implicated in tumor-associated modifications in molecular pathways that control histone gene expression during the cell cycle." (PMID 35281269, 2022).
LSM10 also shares sentences with these, for which no sentence is quoted: adenoid cystic carcinoma (1 paper); colon cancer (1); esophageal carcinoma (1); lung adenocarcinoma (1); Lynch syndrome (1); stomach adenocarcinoma (1); uterine corpus endometrial carcinoma (1).